MYD88 (MYD88 innate immune signal transduction adaptor)
Diseases named in the same sentence as MYD88 in open-access papers (continued):
Sharing a sentence is not in itself a finding about the gene and the disease.
colon carcinoma (21 papers, 2007 to 2024). "Ubiquitin D (Ubd), which is associated with progression of colon cancer, was also significantly expressed genes in Myd88−/− in response to H. felis infection." (PMID 28201999, 2017). "In contrast, a protective role of MyD88 was described for chronic colitis-associated colon cancer formation and gastric cancer development following infection with Helicobacter." (PMID 28662055, 2017). "In addition, the loss of MyD88 accelerates the development of colon tumors induced by azomethane-glucan sulfate sodium and stimulates the development of skin and liver cancer." (PMID 38785969, 2024). "TLR/MyD88-related pathways widely exist in many cancers, like liver cancer and colon cancer, regulating the tumor inflammatory microenvironment and development." (PMID 37153547, 2023). "MyD88 was found to be a target for synthetic lethality in colon cancer; it acts as a bridge between inflammatory signaling pathways from TLRs and Ras oncogenic signaling." (PMID 31695691, 2019). "MyD88 inhibition increased colon cancer cell line sensitivity to genotoxic agents in vitro and in vivo, reducing tumor growth and increasing apoptosis." (PMID 31695691, 2019). "Gene expression microarray analysis showed activation of the TLR4/MYD88/NF-κB pathway in colon cancer cells upon infection with F. nucleatum, and in vitro experiments confirmed that F. nucleatum regulates miRNA 21 expression via the TLR4/MYD88/NF-κB pathway." (PMID 28632155, 2017). "For instance, the TLR2/MyD88 axis has been recognized as a critical regulator of self-renewal of mammary and intestine epithelium as well as breast and colon cancer tumorigenesis." (PMID 28662055, 2017). "The complex role of MyD88 in carcinogenesis is best typified by studies in colon cancer models showing contradictory roles in the same tissue." (PMID 28201999, 2017). "They believed that MyD88 is an independent predictor of poor prognosis in colon cancer." (PMID 38785969, 2024). "Our results showed that the MyD88 signaling blockade might play an essential role in correcting enteric microbiota dysbiosis in colon tumors by up-regulating Hp and SAA3." (PMID 38110638, 2023). "Both TLR4 and its adapter MyD88 are increased in human sporadic colon cancer compared to surrounding normal and adenomatous epithelium, and are associated with poor patient prognosis, thereby implying a functional role for the LPS-TLR4-NF-κB pathway in colon cancer." (PMID 25978030, 2015). "Similar results were reported in a study that investigated the role of MyD88 in colon cancer." (PMID 20871832, 2010). "Furthermore, stimulation of HT-29 (human colon cancer cell line) and WiDr (colon adenocarcinoma line) cells with IL-36α and IL-36γ activate a signaling cascade through MyD88 adaptor protein complex (MyD88, TRAF6, IRAK1, and TAK1), phosphorylation of MAPKs and activation of NF-kB and AP-1." (PMID 30987081, 2019). "However, the role of MyD88 in colon cancer development is more complicated." (PMID 31695691, 2019). "MyD88 deficiency leads to decreased carcinogenesis in noninflammatory model of colon cancer." (PMID 20871832, 2010). "P. distasonis could suppress the production of proinflammatory cytokines in a colon cancer cell line and exhibited anti-inflammatory and antitumor properties through downregulation of TLR4/MYD88/Akt signaling and stimulation of apoptosis." (PMID 37655344, 2023). "It has been recently found, that MyD88 displays anti-apoptotic functions in colon carcinoma cells through the Ras/Erk, but not the NF-κB pathway." (PMID 35551547, 2022). "In addition, in colon cancer, andrographolide represses cell proliferation, elevates cell apoptosis, and activates caspase-3/9 in SW620 human colon cancer cells by inhibiting NF-κB, TLR4, MyD88, and MMP-9 signaling activation." (PMID 31242947, 2019).
colon carcinoma (continued). "Surprisingly, the butyrate-producing bacterium Fusobacterium nucleatum does not consistently inhibit colon cancer; instead, it may promote cancer progression via mechanisms such as TLR4/myeloid differentiation primary response 88 (MYD88)/NF-κB signaling." (PMID 38792581, 2024).
depression (21 papers, 2019 to 2026). "To determine whether MyD88 is involved in promoting depression-like behavior, we subjected wild-type and MyD88-deficient mice to the FST." (PMID 33790733, 2021). "Modulating the GM with XCHT downregulated the TLR4/MyD88/NF-κB pathway, inhibiting tumor growth and improving systemic inflammation in a depression-comorbidity model." (PMID 41561086, 2025). "In summary, Fructus arctii mitigates depression by regulating the let‐7e/TLR4/MyD88 pathway, offering new insights into potential depression therapies." (PMID 39538967, 2024). "In summary, our findings demonstrate that Fructus arctii mitigates depressive disorder via the let‐7e‐mediated TLR4/MyD88 signaling pathway, suggesting its potential as a therapeutic agent for depression." (PMID 39538967, 2024). "The most critical finding of our in vivo study was that Gps improved CUMS-induced depression-like behavior through promoting microglial states into the anti-inflammatory phenotypes likely by inhibiting the TLR4/MyD88/NF-κB signaling pathway." (PMID 35370734, 2022). "In the present study, we observed that the inflammatory immune activation accompanied by microglial reactivity, and TLR4/MyD88/NF-κB signaling were activated in a CUMS-induced depression mice model and LPS-exposed BV-2 cells." (PMID 35370734, 2022). "The current results highlight MyD88 as a novel pharmacological target for treating depression." (PMID 33790733, 2021). "It has been proposed that neuroinflammation-related activation of TLR4/Myd88/NF-κB signaling pathway in the hippocampus might play an important role in partially mediating LPS-induced depression-like behaviors." (PMID 34299230, 2021). "We found that MyD88 may play a role in mediating psychological stress in the brain and may be a key molecule in the linkage between inflammation and depression." (PMID 33790733, 2021). "Therefore, it may also be possible that defective MyD88 signaling would increase neurogenesis, which may affect depression." (PMID 33790733, 2021). "LLE improved CRS-induced anxiety- and depression-like behaviors, reduced microglial activation in the hippocampus, and suppressed TLR4/MyD88/NF-κB signaling and downstream cytokine release (TNF-α, IL-6, IL-1β)." (PMID 42255668, 2026). "In a study using a CUMS model of depression, the TLR4/MyD88/NF-κB and HIF-1α-VEGF signaling pathways in the hippocampus underwent significant changes, contributing to neuroinflammation and depressive behaviors." (PMID 40149760, 2025). "Quinoa saponin shows potential as a natural dietary supplement for the treatment and prevention of anxiety and depression by regulating the MGB axis and inhibiting the activation of the TLR4/MyD88/NF-κB pathway." (PMID 40936908, 2025). "And the antidepressants obviously alleviated CUMS-induced depression-like behavior and exerted considerable neuroprotective effects by regulating the microglial state transition by inhibiting the TLR4/MyD88/NF-κB signaling pathway." (PMID 37917302, 2024). "In summary, our data demonstrated that MOs alleviate experimental depression and inflammation via the E2F2-mediated MyD88/PI3K signalling pathway." (PMID 36052143, 2022). "Our results showed that the expression levels of TLR4, MyD88, NF-κB-p65, TAK1, IRAK1, TRAF6, inflammasome-related NLRP3, ASC, and caspase-1 were all increased in rats of the depression model group." (PMID 33505499, 2021). "In conclusion, RVX in a dose-dependent manner possesses potent ameliorative effects against depression by reducing the oxidative stress and inflammatory process, through the regulation of the TLR4/Myd88/NF-kβ signaling pathway." (PMID 34630092, 2021). "RVX, in a dose-dependent manner, possesses potent ameliorative effects against depression by decreasing oxidative stress, inflammation, and regulating the TLR4/Myd88/NF-kβ signaling pathway." (PMID 34630092, 2021).
depression (continued). "Escin, a natural triterpenoid saponin from Aesculus chinensis (Suoluozi), alleviates CUMS-induced depression-like behaviors by modulating both the BDNF/TrkB/CREB and Toll-like receptor 4 (TLR4)/Myeloid differentiation factor 88 (MyD88)/NF-κB signaling pathways." (PMID 40936908, 2025). "Our study demonstrated that sinisan significantly alleviated the symptoms of IBS-D and ameliorated intestinal dysfunction and depression-like behavior in mice, which may be achieved by inhibiting the TLR4/MyD88/NF-κB pathway." (PMID 39408592, 2024). "The MyD88/PI3K pathway is an important pathway for regulating inflammation and depression." (PMID 36052143, 2022). "It is noteworthy that CMS mice exhibited higher MyD88 expression and phosphorylation levels of PI3K, AKT and NF-κB p65 than nonstressed controls (p < 0.01), which suggested the activation of MyD88/PI3K signalling in depression." (PMID 36052143, 2022). "It is suggested that muscone may alleviate IL-1β-related CNS inflammation through TLR4/MyD88 and TLR4/NLRP3 pathways, thereby attenuating LPS-induced depression-like behaviors." (PMID 35923544, 2022). "However, MO intervention greatly normalized the mRNA expression and protein levels of the MyD88/PI3K axis, reflecting the importance of this signalling pathway in MO-induced anti-inflammatory effects on depression." (PMID 36052143, 2022). "Several reports have supported the notion that inhibiting cytokine release and/or interrupting the TLR4/Myd88/NF-κB signaling pathway may be effective in reducing the magnitude of LPS-induced depression-like behavior, but not LPS-induced sickness." (PMID 34299230, 2021).
ischemic stroke (21 papers, 2017 to 2025). A stroke disorder caused by obstruction of blood flow to the brain, due to thrombotic (local blood clot formation) or embolic (due to a blood clot or other material traveling from another site) event. "Considering that MyD88 activation may enhance neuroinflammation caused by ischemic stroke, we hypothesized that TJ-5 might potently inhibit neuroinflammation to protect against CIRI." (PMID 36588708, 2022). "In conclusion, our preliminary studies indicate that Evobrutinib can inhibit M1 microglial polarization via the TLR4/MyD88/NF-κB pathway, mitigate neuroinflammation, and potentially serve as a therapeutic agent for ischemic stroke." (PMID 40263985, 2025). "To summarize, the use of TEAS can suppress the activation of microglia and levels of inflammation, apoptosis, and pyroptosis in neuronal cells following ischemic stroke via suppressing the TLR4/MyD88/NF-κB pathway." (PMID 38273974, 2023). "In conclusion, TEAS can reduce cerebral damage and suppress inflammation, cell death, and microglia activation after ischemic stroke via inhibiting the TLR4/MyD88/NF-κB pathway." (PMID 38273974, 2023). "The expression of TLR-4, MyD88, and NF-κB was significantly upregulated in the vehicle group; however, these ischemic stroke-induced changes were markedly reversed by treatment with MFSCE (p < 0.05)." (PMID 35454994, 2022). "Collectively, our data provide the evidence that miR-669c-3p is protective in a mouse model of ischemic stroke through enhancement of the alternative microglial/macrophage activation and inhibition of MyD88 signaling." (PMID 32560730, 2020). "We demonstrate novel binding partners for miR-669c-3p with the functional relevance in ischemic stroke and provide the evidence that this miRNA decreases in vivo expression of one of its targets, MyD88." (PMID 32560730, 2020). "This dual action—attenuating MyD88-dependent cytokine storms and stabilizing vascular integrity—aligns with ischemic stroke pathophysiology, particularly in subacute phases where controlled Tlr2 inhibition may balance inflammatory resolution and angiogenesis." (PMID 41354822, 2025). "Moreover, a previous study has reported that Dioscin suppresses ischemic stroke‐induced inflammation by TLR4/MyD88/NF‐κB signal pathway in a rat model." (PMID 38775678, 2024). "Interestingly, previous research has shown that miR-669c-3p has a protective effect in a mouse model of ischemic stroke by enhancing alternative microglia/macrophage activation and inhibiting MyD88 signaling." (PMID 38089628, 2023). "Recent research has demonstrated that mesencephalic astrocyte derived neurotrophic factor (MANF) inhibits the production of proinflammatory factors and relies on the TLR4/MyD88/NF-B pathway to maintain the integrity of the blood-brain barrier in a geriatric mouse model following an ischemic stroke." (PMID 38020537, 2023). "Moreover, LPS, which is a TLR4 agonist, counteracted the impacts of TEAS, indicating that the TLR4/MyD88/NF-κB pathway exerts vital effects on the defensive mechanisms of TEAS against ischemic stroke." (PMID 38273974, 2023). "Hence, the TLR4/MyD88/NF-κB signaling pathway has the ability to control inflammation in neuronal cells following ischemic stroke." (PMID 38273974, 2023). "As the downstream of MyD88, the different roles of NF-κB activity in the early and late stages of ischemic stroke may be an explanation." (PMID 36588708, 2022). "The results indicated that the potent anti-inflammatory effects of the dual-targeting nanoformulation against ischemic stroke might attribute to its blockade of HMGB1/TLRs/MyD88/TRIF/NF-κB signaling pathways." (PMID 35518053, 2019). "Stimulation of TLR4/MyD88 signaling is important for inflammatory responses in ischemic stroke." (PMID 29234386, 2017).
ischemic stroke (continued). "In addition, EA treatment prevented nuclear translocation of NF-κB p65 and suppressed expression of p38 MAPK and myeloid differentiation factor 88 (MyD88) in the peri-infract sensorimotor cortex during ischemic stroke." (PMID 29163038, 2017). "Since inflammatory responses contribute to hypoxic injury and importance of TLR4 in inflammatory mechanisms has been well recognized, blocking TLR4/MyD88 signaling pathway may be a potentially neuroprotective therapeutic strategy for ischemic stroke." (PMID 29234386, 2017). "This study was to explore whether transcutaneous electrical acupoint stimulation (TEAS) treatment could mediate inflammation, apoptosis, and pyroptosis of neuronal cells and microglia activation through the TLR4/MyD88/NF-κB pathway in the early stage of ischemic stroke." (PMID 38273974, 2023). "Hence, blocking the TLR4/MyD88/NF-κB pathway is a crucial approach to diminish neuronal cell inflammation, while also suppressing apoptosis and pyroptosis levels, ultimately easing the impact of ischemic injury in cases of ischemic stroke." (PMID 38273974, 2023). "Therefore, short-term inhibition of MyD88 attenuates cerebral damage in ischemic stroke." (PMID 36588708, 2022). "Previous research has revealed that after ischemic stroke, activated the signaling pathway of TLR4/MyD88/NF-κB increases the production of inflammatory mediators." (PMID 39962509, 2025). "In addition, EA treatment inhibits microglia-mediated neuroinflammation through inactivation of p38 MAPK and MyD88, accompanied by the decrease of IL-1β, IL-6, and TNF-α after ischemic stroke." (PMID 31866829, 2019). "Mechanistically, the anti-neuroinflammatory effects of SAD in ischemic stroke may be attributed to its inhibitory action on high mobility group box 1 (HMGB1) nuclear-to-cytoplasmic translocation and subsequent blockade of the TLR4/MyD88/NF-κB signaling cascade activation." (PMID 40756985, 2025).
malaria (21 papers, 2009 to 2025). Malaria is a serious and sometimes fatal disease caused by a parasite that commonly infects a certain type of mosquito which feeds on humans. "Here, this study reveals that cGAS‐STING signaling plays a detrimental role in regulating anti‐malaria immunity by cooperating with MyD88 to induce p38‐dependent late IL‐6 production and expanding CD11b+Ly6Chi proinflammatory monocytes." (PMID 35635376, 2022). "MyD88, together with TLR7 or TLR9, has been associated as a protective factor for immunity to malaria." (PMID 30761111, 2019). "Overall, our data argue that the IFN-γ, TNF-α and MyD88 role on hypersensitivity to septic shock during malaria is, at least in part, mediated by inflammasome-dependent release of IL-1β." (PMID 24453977, 2014). "The essential role for MyD88 signalling for macrophage activation by malaria-infection derived MPs is entirely consistent with a number of studies demonstrating a role for MyD88 in malarial inflammation and pathology." (PMID 20126448, 2010). "This suggests that another MyD88 dependent receptor such as IL-1R is involved and supports a role for IL-1β in malaria-related pathology." (PMID 19696895, 2009). "Additionally, in the A3SA_36 vs. A3SA_24 comparison, we noted the down-regulation of MyD88, a regulator of NF-κB, in ‘malaria (ko05144)’ and ‘shigellosis (ko05131)’, leading to the inhibition of the antibacterial NF-κB pathway." (PMID 38673764, 2024). "The cGAS/STING activation recruits myeloid differentiation factor 88 (MyD88) and specifically activates the p38-dependent signaling pathway to produce late IL-6, which expands CD11b+Ly6Chi proinflammatory monocytes to inhibit anti-malaria immunity." (PMID 36825026, 2023). "This may make biological sense, as infection of hepatocytes by malaria sporozoites has been shown to induce the activation of NF-κB in a MyD88 specific manner." (PMID 21912619, 2011). "However, SOCS1 deficiency could not protect host from infection in Myd88−/− mice, suggesting that SOCS1 controls the host resistance to malaria mainly through MyD88-mediated IFN-I production." (PMID 33363057, 2020). "To define whether and to which extent any of these sensing pathways control systemic type I IFN secretion during severe malaria in vivo, we first inoculated Myd88-/-, StingGt/Gt or control WT mice with Py YM, and measured blood and bone marrow IFNα/β levels at its peak (d 1.5) of production." (PMID 27792766, 2016). "It has been reported that lipid metabolism is significantly elevated during intraerythrocytic development of malaria parasites infected, which mainly through the TLR/MyD88 signaling pathway." (PMID 40045630, 2025). "The inhibitory effect of HD5 on oocyst development decreased slightly when MyD88 expression was silenced by RNAi, indicating that the Toll signaling pathway plays a role in the HD5-mediated transmission blocking of malaria." (PMID 39195607, 2024). "Altogether, these results establish the importance of both MyD88 and STING sensing pathways for systemic pDC-derived type I IFN production during severe blood stage malaria." (PMID 27792766, 2016). "Altogether, these data establish pDCs as key producers of type I IFN in the course of severe malaria, through the TLR7/MyD88 pathway." (PMID 27792766, 2016). "Activation of TLR9 by A-type CpG DNA leads to induction of IFNA in pDCs through a MYD88- and IRF7-dependent mechanism, and previous work similarly found TLR9-dependence of IFNA production in pDCs during in vitro infection with malaria parasites." (PMID 23144737, 2012). "It was recently reported that malaria-induced priming of the TLR response was TLR9-, MyD88-, and IFN-γ-dependent." (PMID 22463100, 2012). "MyD88 and STING, and pDCs accounted for systemic type I IFN production in severe malaria." (PMID 27792766, 2016).